ALB (albumin)
Diseases named in the same sentence as ALB in open-access papers (continued):
Sharing a sentence is not in itself a finding about the gene and the disease.
dyslipidemia (258 papers, 2010 to 2026). "Low albumin levels have also been linked to increased cardiovascular risk and mortality in metabolic syndrome, making it an important marker for both liver and systemic disease severity." (PMID 40954485, 2025). "Multivariable analysis identified dyslipidemia, postoperative sodium delta, and postoperative increase in direct bilirubin as independent risk factors for complications, whereas albumin demonstrated a protective effect." (PMID 41464562, 2025). "High age, male sex, low glomerular filtration rate (all P<0.001), high albumin-creatinine ratio, White race (P=0.006 for both), dyslipidemia (P=0.042), and current smoking (P=0.044) were associated with CACS>0." (PMID 40862459, 2025). "In women, the albumin level was positively associated with dyslipidemia and inversely associated with high BMI." (PMID 37700384, 2023). "Our study found that both urinary A-megalin and albumin were independently associated with the clustering numbers of metabolic syndrome traits in Japanese adults." (PMID 35033174, 2022). "Factors associated with bone mass loss include a history of fragility fractures and maternal hip fractures, whereas factors associated with muscle mass loss include low albumin levels, angiotensin-converting enzyme inhibitor use, and dyslipidemia." (PMID 36294493, 2022). "In age- and sex-adjusted logistic regression analysis, A-megalin and albumin were significantly associated with the clustering number of metabolic syndrome traits (3 or more)." (PMID 35033174, 2022). "The risk of dyslipidemia was significantly higher among people whose albumin level was higher than 46.6 g/L (P for interaction = 0.014)." (PMID 35872922, 2022). "We found that urinary A-megalin and albumin were each independently associated with the clustering number of metabolic syndrome traits." (PMID 35033174, 2022). "Biochemical abnormalities were primarily reflected by liver function-associated indicators such as albumin and alkaline phosphatase levels; dyslipidemia, such as cholesterol and triglyceride levels; and electrolyte and trace element disturbances." (PMID 35957897, 2022). "Although we used albumin corrected calcium in our study, our albumin-stratified analyses still showed that the risk of dyslipidemia attributed to [Ca2+]corr was significantly higher among people with higher albumin levels." (PMID 35872922, 2022). "Both urinary A-megalin and albumin are associated with the clustering number of metabolic syndrome traits." (PMID 35033174, 2022). "The association between APOE and APOC1 variants and metabolic syndrome and serum albumin levels further supported the crucial role of APOE region variants in cardiometabolic disorders in a Taiwanese population." (PMID 36011277, 2022). "APOE rs429358 and APOC1 rs438811 were also independently associated with metabolic syndrome (p = 2.29 × 10−14) and serum albumin levels (p = 3.80 × 10−6), respectively." (PMID 36011277, 2022). "Our data also indicated that APOE and APOC1 variants were independently associated with metabolic syndrome and serum albumin levels, respectively." (PMID 36011277, 2022). "Genotype–phenotype association analysis revealed a significant association of rs429358 and rs438811 with metabolic syndrome and of rs7412, rs438811, and rs439401 with serum albumin levels (p < 0.0015)." (PMID 36011277, 2022). "Our data also provide evidence for the association of APOE locus variants with metabolic syndrome and serum albumin levels." (PMID 36011277, 2022). "In this study, we found that that presence of metabolic syndrome did increase the risk of low-grade albuminuria, a finding that can provide valuable insight into the definition of normal reference values for urine albumin excretion." (PMID 33686966, 2021).
dyslipidemia (continued). "In the age-, sex-, and BMI z-score-adjusted model (Model 1), the highest categories of serum calcium and albumin-corrected calcium levels were both associated with higher probabilities for dyslipidemia, using the middle category as the reference." (PMID 34434908, 2021). "Multivariable-adjusted odds ratios and 95% confidence intervals of serum calcium and albumin corrected calcium associated with dyslipidemia." (PMID 34434908, 2021). "In summary, we have found that donors are at risk to develop features of the metabolic syndrome and increased urine albumin excretion, in addition to the expected mild reduction of GFR." (PMID 30704441, 2019). "The dyslipidemia is due to a combination of increased liver synthesis of albumin and lipoprotein to compensate for urinary loss of albumin, and disturbance in the metabolism of cholesterol." (PMID 30761277, 2019). "The variables associated with multiple plaques were age, smoking, dyslipidemia, advanced stages of retinopathy, pulse pressure and albumin creatinine ratio." (PMID 29728117, 2018). "In conclusion, increase in serum albumin concentration was independently associated with lower risk of developing prediabetes especially IFG or IA1c even after eliminating the effect of metabolic syndrome." (PMID 28430803, 2017). "Association between weighted serum albumin, uric acid, neutrophils levels and metabolic syndrome." (PMID 39480760, 2024). "Alongside this overshooting inflammatory state, metabolic alterations occur, and dyslipidemia stands out, with increased levels of circulating free fatty acids, causing an imbalance in the molar ratio of circulating fatty acids/albumin, triggering lipotoxicity events in various tissues." (PMID 37512868, 2023). "Furthermore, the ALMI was negatively associated with metabolic syndrome (MetS) in women after adjustments for age, BMI, ethnicity, albumin, vitamin D, energy intake, drinking, smoking, and physical activity." (PMID 37176623, 2023). "Considering ionized calcium [Ca(2+)] is the best measure of active serum calcium and the lack of Ca(2+) analyzers, we aimed to examine the independent and joint associations between serum ionized calcium corrected by albumin ([Ca2+]corr) and the known modifiable risk factors and dyslipidemia." (PMID 35872922, 2022). "After further adjustment with eGFR, higher quartiles of A-megalin and albumin were each independently associated with the clustering number of metabolic syndrome traits (adjusted odds ratio for A-megalin: 1.30 per quartile, 95% CI 1.03–1.64; albumin: 1.42 per quartile, 95% CI 1.12–1.79)." (PMID 35033174, 2022). "However, the risk of dyslipidemia only showed a monotonically increasing tendency when the albumin-corrected calcium level was beyond 2.50 mmol/L after adjustment of confounding factors as well (p for nonlinear < 0.001)." (PMID 34434908, 2021). "Moreover, high albumin levels have previously been associated with metabolic syndrome." (PMID 31687055, 2019). "Blood biochemistry showed kidney dysfunction, dyslipidemia, increased alkaline phosphatase and glutamyltransferase, and decreased albumin." (PMID 41496093, 2026). "In an elderly Spanish population study targeting metabolic syndrome, higher PRAL and NEAP scores were associated with decreased eGFR and increased urine albumin creatine ratio (UACR) after 1 year of follow-up." (PMID 40474901, 2025). "Factors such as metabolic syndrome, nutritional status, hypertension, dyslipidemia, increased body mass index (BMI), and lower albumin levels are considered key contributors to the heightened risk of AKI development." (PMID 40911105, 2025). "Since NAFLD is a metabolic disease often co-occurring with factors like insulin resistance, excess weight, and other metabolic syndromes, maintaining adequate albumin levels is critical to support overall metabolic health and prevent disease exacerbations." (PMID 39996009, 2025).
dyslipidemia (continued). "Within a certain range, high levels of ALB and DBIL can reduce the risk of dyslipidemia in these children." (PMID 38628642, 2024). "Independent predictors of secondary renal endpoints were dyslipidemia, hemoglobin, urine albumin, and eGFR." (PMID 38927457, 2024). "In vivo experiments demonstrated that AS-IV significantly reduced hyperglycemia, dyslipidemia, urinary albumin excretion, and serum creatinine levels in DKD rats." (PMID 38572426, 2024). "All of these observations align with the findings of our study, indicating that ALB serves as a protective predictor of dyslipidemia in children with epilepsy." (PMID 38628642, 2024). "ALB (OR = 0.913,95% CI: 0.836–0.997, p = 0.043) and DBIL (OR = 0.511,95% CI: 0.307–0.850, p = 0.01) were also independent protective factors of dyslipidemia in children with epilepsy caused by VPA." (PMID 38628642, 2024). "Luckily, direct protective effects of YBD were observed in PAN-induced rats, including reducing proteinuria, decreasing blood pressure, increasing urine volume and ALB, ameliorating the condition of renal function and dyslipidemia." (PMID 39311772, 2024). "Despite widespread access to lipid-lowering medications, a significant portion of American adults suffer from dyslipidemia, suggesting that elevated serum lipid levels are prevalent globally, even in individuals expressing normal albumin levels." (PMID 39123208, 2024). "Concomitantly, the development of a peculiar metabolic disorder characterized by dyslipidemia, with increased levels of circulating free fatty acids and an imbalance in the fatty acid/albumin molar ratio, triggers events of cellular lipotoxicity." (PMID 37512868, 2023). "Through comparison with traditional urinary biomarkers, including urinary albumin, we sought to identify potential novel urinary biomarkers that are related to the clustering of metabolic syndrome traits." (PMID 35033174, 2022). "The rs1260326 was the most common lead SNP for lipid profile, blood pressure status, fating plasma glucose, serum uric acid, albumin, and AST levels, urine albumin levels, and metabolic syndrome." (PMID 35328045, 2022). "Participants with a higher number of metabolic syndrome traits were likely to have higher β2-MG (P trend = 0.024) and higher albumin, α1-MG, and NAG (all P trend < 0.001)." (PMID 35033174, 2022). "Summing all the factors, age, medication for blood pressure and dyslipidemia, albumin, glucose, wake period diastolic hypertension, LDL cholesterol, self-reported physical activity were the top predictors across multiple models." (PMID 35058500, 2022). "After adjustment for age and sex, A-megalin and albumin had significantly higher odds ratios of a higher clustering number of metabolic syndrome traits." (PMID 35033174, 2022). "We also investigated if the association between [Ca2+]corr and dyslipidemia odds was modifiable by age, gender, waist circumstance, BMI, eGFR, ALT, AST or albumin using stratified analyses." (PMID 35872922, 2022). "A modifiable effect of albumin on the relationship between [Ca2+]corr and dyslipidemia odds was also found (P for interaction = 0.014)." (PMID 35872922, 2022). "An increasing tendency in the rate of dyslipidemia both in serum calcium level and albumin-corrected calcium was observed, which was only statistically significant for albumin-corrected calcium (p for trend < 0.001)." (PMID 34434908, 2021). "Previous research has confirmed the positive correlation between serum albumin level and metabolic syndrome." (PMID 34836106, 2021). "Multivariable logistic regression models were applied to calculate odds ratios (ORs), with 95% confidence intervals (CIs), for dyslipidemia of each serum calcium level and albumin-corrected calcium levels, which were sorted into quartiles." (PMID 34434908, 2021). "The serum calcium and albumin-corrected calcium level in those with dyslipidemia were higher than those in healthy children." (PMID 34434908, 2021).
dyslipidemia (continued). "Actually, the oxidative state of ALB is reportedly modulated in metabolic syndrome, inflammation, and immunoglobulin A nephropathy." (PMID 33329359, 2020). "The lowest tertile of BDNF was associated with higher age, fewer cases of metabolic syndrome, lower levels of RBMT score, diastolic blood pressure, albumin, Hemoglobin A1c, low density lipoprotein, and estimated glomerular filtration rate." (PMID 33020545, 2020). "Trojan horse effect can be exacerbated by an increase in albumin filtration (alterations in glomerular basement barrier) and/or increase in the molar ratio free fatty acid/albumin (e.g., dyslipidemia)." (PMID 32290082, 2020). "In this model, the top five parameters determined by IRF were albumin (100, reference), age, total protein, dyslipidemia, and carvedilol use." (PMID 31499517, 2019). "Donors are at increased risk to develop features of the metabolic syndrome in addition to the expected mild reduction of GFR and increased urine albumin excretion." (PMID 30704441, 2019). "ED is associated with a higher HbA1c, presence of metabolic syndrome, hypertension, atherogenic dyslipidemia, lower estimated glomerular filtration rate, higher albumin/creatinine ratio and more severe small fibre neuropathy in men with T1DM159–161." (PMID 30828432, 2019). "This analysis revealed that the variables associated with the presence of carotid plaques were age (p < 0.001), advanced DR (p = 0.044), smoking (p = 0.013), dyslipidemia (p < 0.001), pulse pressure (p = 0.014), and albumin creatinine ratio (p = 0.013)." (PMID 29728117, 2018). "Patients treated with DPP-4 inhibitors showed significantly higher systolic BP, diastolic BP, serum albumin, serum sodium, dyslipidemia, and eGFR reduction rate (baseline to 3 and 12 months) than the DPP-4 inhibitor-untreated patients did." (PMID 29187821, 2017). "Patients treated with DPP-4 inhibitors showed significantly higher systolic blood pressure (BP), diastolic BP, serum albumin, dyslipidemia, and eGFR reduction rate (baseline to 12 months) than the untreated patients did." (PMID 29187821, 2017). "We also lost subjects by including variables known to be related to aging/mortality, such as the albumin creatinine ratio, heart rate and disease/treatment variables such as treated dyslipidemia, for which completeness ranges between 86% and 90%." (PMID 28422991, 2017). "And SYFSF likely played a better role in decreasing urinary albumin, inflammation, and dyslipidemia than irbesartan." (PMID 28713834, 2017). "Regarding the biomarkers evaluation, people over 65 had lower albumin levels as well as less insulin resistance and dyslipidemia." (PMID 26159840, 2015). "Obviously, among examined modified forms of albumin, only AOPP were an independent risk factor for metabolic syndrome occurrence in the studied population." (PMID 24957167, 2014). "The effects of dyslipidemia in the context of sitagliptin treatment were next examined by quantifying urinary albumin and 8-hydroxy-2-deoxyguanosine (8-OHdG) excretion levels." (PMID 24972137, 2014). "In addition to elevated blood glucose levels and dyslipidemia, the urinary albumin-creatinine ratio was significantly increased in the urine of diabetic mice." (PMID 41030909, 2025). "Future prospective studies incorporating detailed pharmacological records (to account for statin use) and nutritional status indicators (e.g., albumin, BMI) are necessary to validate the mechanism behind the protective dyslipidemia paradox observed in this cohort." (PMID 41388514, 2025). "Another study found that insomnia symptoms with major depression may be associated with higher body mass index and waist circumference and lower levels of metabolic syndrome components, triglycerides, insulin, and albumin." (PMID 40427032, 2025). "Metabolic syndrome has been reported to be a factor strongly correlated with urinary albumin, and albuminuria may be missed in many cases in hyperuricemic patients with metabolic syndrome." (PMID 40839334, 2025).
dyslipidemia (continued). "Interestingly, research has demonstrated that ALB infusion helps alleviate dyslipidemia in models of anaplastic anemia, providing compelling evidence for the positive role of serum albumin in regulating lipoprotein metabolism." (PMID 38628642, 2024). "The findings in this study suggest that all forms of dyslipidemia are associated with increased HALP score, pointing at individual or combined alterations in any of the four indexes of HALP score, namely hemoglobin, albumin, lymphocyte, and platelet." (PMID 38004051, 2023). "After adjustments for sex, age, BMI, and diabetic duration, the associations among HbA1c, ALT, serum ALB, eGFR, urinary ACR, VPT, HSL, presence of dyslipidemia, NAFLD, DPN, DN, PAD and AAR were attenuated but remained statistically significant (P<0.01 or P<0.05)." (PMID 36909318, 2023). "Specifically, 11 different groups of serum biomarkers were analyzed to evaluate their association with metabolic syndrome [urea, hs-RCP, cholesterol (COL, HDL, LDL), TG, HCY, Lpa, GOT, GPT and albumin] as these are the most analyzed inflammatory biomarkers in the CVD field." (PMID 36860672, 2023). "Thus, GA (albumin bound to glucose) will also increase under conditions of hyperglycemia and dyslipidemia." (PMID 35942243, 2022). "Our data revealed that multiple low-frequency and rare GCKR exonic mutations are also significantly associated with serum triglyceride and albumin levels and metabolic syndrome, independent of rs1260326 genotypes." (PMID 35328045, 2022). "The RKFD group had a higher prevalence of metabolic syndrome and central obesity; higher levels of eGFR, eGFRcr-cys, urine albumin-creatinine ratio (UACR), fasting glucose, insulin, HOMA-IR, and FGF-23; and lower levels of total cholesterol, LDL, and serum creatinine than the group without RKFD." (PMID 36671416, 2022). "Although other components of the metabolic syndrome that underlies T2DM can act as determinants of CVD, this is the first demonstration that serum albumin can modulate lipid flux in macrophages, and that this is under the direct influence of glycemic control in subjects with DM." (PMID 34684632, 2021). "The rate of dyslipidemia and components trends with serum calcium and albumin corrected calcium." (PMID 34434908, 2021). "Variants of the albumin genes family, including the fetal counterpart of serum albumin (AFP) and afamin/alpha-albumin (AFM) genes, are associated with the development of the metabolic syndrome in adult humans." (PMID 32071365, 2020). "For Edoc-A, fourteen files of complete subsamples were created, which were given the following names: albumin, alcohol, waist circumference, cholesterol, creatinine, diabetes, dyslipidemia, hand grip strength, hemoglobin, hypertension, obesity, metabolic syndrome, smoking and triglycerides." (PMID 30726489, 2019). "Dyslipidemia showed an inverse relationship with a low albumin level." (PMID 31196057, 2019). "Moreover, dyslipidemia, oxidative stress and albumin/creatinine ratio were improved by S. suberectus extract treatment." (PMID 30223524, 2018). "Patients who were treated with fimasartan for 1 year showed a significant reduction in blood pressure and urinary albumin excretion, demonstrating that control of metabolic syndrome through ARB-effected blood pressure reduction is an effective means to prevent organ damage." (PMID 29261715, 2017). "In addition to these independent predictors, several other variables were significantly associated with myocardial injury in the univariate analysis, including male sex, preoperative hypotension, complete paralysis, low serum albumin, and dyslipidemia (i.e., low TC and LDL levels)." (PMID 40832466, 2025). "Thus, Angptl4 provides a molecular link between proteinuria and hypertriglyceridemia and could explain the presence of dyslipidemia in patients with near-normal serum albumin levels (as in the present study)." (PMID 38720111, 2024).